IGKV1-8 (immunoglobulin kappa variable 1-8)
Description:
V region of the variable domain of immunoglobulin light chains that participates in the antigen recognition. Immunoglobulins, also known as antibodies, are membrane-bound or secreted glycoproteins produced by B lymphocytes. In the recognition phase of humoral immunity, the membrane-bound immunoglobulins serve as receptors which, upon binding of a specific antigen, trigger the clonal expansion and differentiation of B lymphocytes into immunoglobulins-secreting plasma cells. Secreted immunoglobulins mediate the effector phase of humoral immunity, which results in the elimination of bound antigens. The antigen binding site is formed by the variable domain of one heavy chain, together with that of its associated light chain. Thus, each immunoglobulin has two antigen binding sites with remarkable affinity for a particular antigen. The variable domains are assembled by a process called V-(D)-J rearrangement and can then be subjected to somatic hypermutations which, after exposure to antigen and selection, allow affinity maturation for a particular antigen.
Synonyms: IGKV18; L9
Gene: Immunoglobulin variable (V) gene on chromosome 2 (88,992,409 to 88,992,931, reverse strand). Ensembl gene ENSG00000240671.
Subcellular location: Secreted; Cell membrane
Gene Ontology:
Biological process: immune response
Cellular component: extracellular region; immunoglobulin complex; plasma membrane
Homologues: Orthologues: mouse Igkv15-103 (72% identical). Paralogues in human: IGKV1D-8 (94% identical), IGKV1-9 (90% identical), IGKV1-39 (90% identical), IGKV1D-13 (90% identical), IGKV1D-39 (90% identical), IGKV1-12 (89% identical), IGKV1-6 (89% identical), IGKV1-27 (88% identical), IGKV1D-12 (88% identical), IGKV1D-16 (88% identical), IGKV1D-43 (88% identical), IGKV1-16 (87% identical), and 81 more.